CRP (C-reactive protein)
Diseases named in the same sentence as CRP in open-access papers (continued):
Sharing a sentence is not in itself a finding about the gene and the disease.
Arthritis (continued). "Therefore, ADRB2, AHR, CRP, IRF1, PTGS1, SPP1 and other targets can be used as potential targets for CC in the treatment of arthritis, and it is of great significance to explore its role of CC in the treatment of arthritis." (PMID 37637408, 2023). "Yet thorough examination revealed that many patients had elevations of serum CRP and non-ophthalmological indications to consider systemic immunomodulatory treatment including recurrent headaches, disabling episodes of fatigue, arthritis, abdominal pain, and AA amyloidosis." (PMID 35868845, 2022). "Therefore, we investigated SSc patients with and without elevated CRP levels for prevalence and localization of arthritis." (PMID 36743676, 2022). "However, he continued to have active arthritis and his CRP increased to 102; RF, ACPA, and ANA were negative." (PMID 36199642, 2022). "CRP, ER, MCP-1 and PTX3 may play a significant regulatory role in improving arthritis." (PMID 34447637, 2021). "In the second step, scores of 4 items, arthritis (swelling of the small or intermediate/large joints), serologic test results (rheumatoid factors and anti-CCP antibodies), disease duration (6 weeks or longer), and acute-phase reaction (erythrocyte sedimentation rate and CRP), are weighted and added." (PMID 32944095, 2020). "The respective percentages of patients with elevated CRP (> 5 mg/L) were as follows: S 0%, E 0%, A 20%, SE 7%, SA 33%, EA 27%, and SEA 33%, indicating that only a subset of patients with arthritis, but not patients with skin or entheseal disease show elevated CRP." (PMID 32051028, 2020). "The Jones criteria for rheumatic fever include major criteria (carditis, arthritis, chorea, erythema marginatum, subcutaneous nodules) and minor criteria (polyarthralgia, fever, prolonged PR interval, erythrocyte sedimentation rate (ESR) ≥60 mm, C-reactive protein (CRP) ≥3.0 mg/dL)." (PMID 32098238, 2020). "We can only speculate why in our data physical illness (except pulmonary disease and arthritis), hs-CRP and fibrinogen did not predict future sleep complaints and depressive symptoms." (PMID 29204805, 2018). "Then we investigated whether baseline stress associated with the MRI-detected total inflammation score or CRP at arthritis onset and this revealed non-significant relationships (p = 0.11 and p = 0.92)." (PMID 29724244, 2018). "The lack of CRP at follow-up meant the reverse pathway (fatigue to CRP) could not be simultaneously explored, and we could not include diagnoses at baseline of arthritis." (PMID 28994356, 2018). "Therefore, in RA patients and in other arthritis patients, BMI was neither associated with swollen SJC nor with CRP levels." (PMID 27770823, 2016). "However, measurements of ESR and CRP at baseline were related neither to development of arthritis nor to 14-3-3η positivity in this cohort (data not shown)." (PMID 27037016, 2016). "However, animal studies provide evidence of a protective role of CRP in early arthritis, and CRP-bound antigens in vitro have no pro-inflammatory potential, compared with IgG-ICs." (PMID 26406605, 2015). "The synovial expression of enzymes of the PGE2 pathway was not related to development of arthritis in subjects at risk of developing RA and within RA patients we did not observe a relation with the systemic inflammatory parameters ESR and CRP or with disease persistence." (PMID 26225917, 2015). "However, on multivariate analysis adjusted for the covariates CRP, RF, anti-CCP2 and arthritis of the hand joints, only arthritis of the hand joints and anti-CCP2, at both low and high titers predicted RA, with a risk of 3.2 for low, and 4.3 for high anti-CCP2 titers at baseline." (PMID 23339296, 2013). "Arthritis activity was evaluated by clinical examination, the American College of Rheumatology (ACR) criteria, the Stanford Health Assessment Questionnaire Disability Index (HAQ-DI), and laboratory tests for erythrocyte sedimentation rate (ESR) and C-reactive protein (CRP)." (PMID 20067641, 2010).
Arthritis (continued). "While her CRP levels were 32 mg/L before the start of the new psychotropic treatment regimen, they dropped continuously to 13 mg/L over 10 months between October 2007 and July 2008 without changing the arthritis specific medication." (PMID 20157432, 2010). "However, recent research does not support a significant relationship between CRP and arthritis." (PMID 38347551, 2024). "Also, CRP level was only correlated to the extent of arthritis but not skin disease or enthesitis." (PMID 32051028, 2020). "Notably, her serum CRP (3.3 mg/l) and CPK (63 UI/l) returned to normalized levels despite persisting fatigue, along with arthritis of her metacarpal and proximal interphalangeal joints (arthritis confirmed at a consultation in May 2015)." (PMID 28257650, 2017). "In this review article, we evaluate the role of RA factor or rheumatoid factor (RF), uric acid, C-reactive protein (CRP), and adenosine deaminases (ADAs) as biomarkers in patients with and without arthritis." (PMID 38699124, 2024). "Also, the protective effects of CRP against arthritis were seen irrespective of whether there was only one injection or six injections of CRP before the onset of the disease, that is, before the first mouse in the group developed arthritis." (PMID 38650931, 2024). "Patients with axSpA and IBD had higher levels of disease activity, as assessed by ESR and CRP and ET-1 levels, than did patients with axSpA without IBD, suggesting that the differences were due to IBD activity rather than arthritis activity." (PMID 34240250, 2022). "Clinical evaluation revealed no arthritis, while the laboratory tests showed high ESR and CRP, and positive SARS-CoV-2 test." (PMID 35611100, 2022). "Only a tendency to positive correlation between senescent Th cells and CRP or ESR and a negative correlation between these cells and bone mineral density were found in early arthritis patients." (PMID 33291545, 2020). "After the therapy, the tendon thickness in psoriatic patients with no arthritis was found to be affected by the initial thickness of the nail bed and the nail matrix, duration of the skin disease and initial CRP (C-reactive protein) concentration." (PMID 30558114, 2018). "Except for the CRP, the clinical indexes (including disease duration and ESR) showed no statistical difference between the SLE groups with and without arthritis or between the Gout and HUA groups." (PMID 30046600, 2018). "As per the modified Wallace criteria, inactive disease was defined as absence of active arthritis, fever, and signs or symptoms of SJIA; normal C-reactive protein level; and physician’s global assessment of disease activity ≤10 mm)." (PMID 28115015, 2017). "The C-reactive protein (CRP), unlike the ESR, does not usually rise with disease activity unless there is arthritis or serositis, and a raised CRP in a patient with SLE must always make you consider infection." (PMID 16722594, 2006). "Second, we did not fully examine the association between molecular subgroups and clinical manifestations (fever, rash, arthritis, etc.), laboratory variables (ESR and CRP) and long-term disease course or outcome due to lack of information at an individual level." (PMID 39923112, 2025). "Inactive disease was defined as a state of no joints with active arthritis, no uveitis, no systemic symptoms, normal erythrocyte sedimentation rate (ESR) and/or C-reactive protein (CRP), and a physician’s global assessment of disease activity indicating no disease activity." (PMID 31661011, 2019). "Similarly, in other studies of children with arthritis, ESR and CRP did not correlate with BMI." (PMID 22240096, 2012).
bacteremia (384 papers, 2006 to 2026). "Univariate regression revealed that both the first and second CRP were significantly associated with bacteremia." (PMID 40809608, 2025). "Both in first-line and first- and second-line treatments, non-effective episodes were associated with higher age, heavier body weight, higher CRP level at entry, stem cell transplantation, and bacteremia." (PMID 40626871, 2025). "The authors concluded that IL-6 was the best predictor for identifying patients at risk of bacteremia or prolonged fever episodes, outperforming both IL-8 and CRP in diagnostic accuracy." (PMID 40647525, 2025). "This study examined the relationship between C-reactive protein/serum albumin ratio and Q Pitt bacteremia score with all-cause in-hospital mortality in patients with bloodstream infections." (PMID 39252713, 2024). "Our AUROC was 0.689, which aligns with previous studies indicating that CRP is a poor diagnostic test for bacteremia in patients with UTI." (PMID 38542009, 2024). "The relationship between C-reactive protein/albumin ratio and quick Pitt bacteremia score with all-cause in-hospital mortality was determined." (PMID 39252713, 2024). "The NLR has a strong association and equivalent effectiveness in identifying bacterial sepsis in emergency care settings when compared to other biomarkers, such as CRP and procalcitonin." (PMID 38792936, 2024). "A more recent study, also employing MVA, identified bilirubin, along with CRP, respiratory rate, and procalcitonin as factors independently associated with bacteremia." (PMID 39202194, 2024). "Proposed mechanisms include bacteremia and the associated systemic inflammatory sequelae, including higher C-reactive protein (CRP) values and oxidative stress." (PMID 38535432, 2024). "Of the markers used clinically, C-reactive protein (CRP) shows high diagnostic sensitivity but has low specificity for bacteremia." (PMID 39457628, 2024). "This study examined the relationship between C-reactive protein/serum albumin ratio and qPitt bacteremia score and all-cause in-hospital mortality in patients with BSIs admitted at an academic, referral hospital in Oman." (PMID 39252713, 2024). "Analysis of C-reactive protein levels in blood after the initiation of appropriate antibiotic treatment reflected the favorable treatment outcomes and showed that bacteremia was associated with a stronger inflammatory response." (PMID 38294118, 2024). "Logistic regression analysis showed that higher BT at triage, higher pulse rates at triage, higher neutrophil counts, and higher CRP levels were all associated with increased odds of bacteremia." (PMID 37679686, 2023). "In brief, PCT has a higher diagnostic reliability when compared to CRP in the diagnosis of bacterial sepsis in patients with autoimmune disease, and PCT is more specific than sensitive." (PMID 37296721, 2023). "In infants aged 30–59 and 60–90 days, higher neutrophil and CRP levels were associated with bacteremia." (PMID 37679686, 2023). "After adjusting for other covariates, age between 30 and 59 days, higher BT at triage, higher neutrophil count, and higher CRP levels were associated with bacteremia." (PMID 37679686, 2023). "Bacteremia was confirmed in 32 of 92 patients, and they showed that both presepsin and PCT had good diagnostic accuracy in predicting bacteremia, superior to CRP." (PMID 36072944, 2022). "In this study, blood biochemistry values associated with disease progression included: CRP (elevated during bacteremia); lactate, AST and ALP (peaked at 18 dpi); and TBIL (highest at 6–12 dpi)." (PMID 35925895, 2022). "ROC curve analysis demonstrated that PCT was superior to presepsin and CRP as a diagnostic biomarker, and it had higher sensitivity and negative predictive value for predicting culture-proven bacterial infection and bacteremia." (PMID 36072944, 2022).
bacteremia (continued). "The proposed mechanisms include bacteremia and the associated systemic inflammatory sequelae, including elevations in C-reactive protein (CRP) and oxidative stress." (PMID 33419028, 2021). "Since 2017 we have been using procalcitonin and IL‐6, both having higher a diagnostic power for determining bacterial sepsis in children compared to CRP." (PMID 33108806, 2021). "Diagnostic accuracy of C-reactive protein (N = 3,751) and procalcitonin (N = 1,251) to predict bacteremia." (PMID 34746044, 2021). "PCT has been identified as a marker of bacterial sepsis and serious infections with a higher diagnostic accuracy than CRP." (PMID 34828740, 2021). "In univariate logistic regression analysis, neutropenia, HSCT, PCT level, and CRP level were significantly associated with bacteremia (all P < 0.05)." (PMID 31821331, 2019). "This study on the diagnostic accuracy of PCT and CRP for bacteremia in hematologic patients including patients with neutropenia or HSCT is one of the largest studies conducted up to date." (PMID 31821331, 2019). "An infection is an important source of inflammatory stimuli and thus promotes the production of CRP, which can then be used clinically as a diagnostic parameter for infection and bacterial sepsis." (PMID 30842764, 2019). "An older study identified an elevated CRP value as a risk factor for bacteremia in chronic hemodialysis patients but this study was independent of catheter implantation." (PMID 31151433, 2019). "Multivariate analysis disclosed that the Pitt bacteremia score and C-reactive protein value at disease onset were independent factors associated with increased incidence of 30-day mortality (aOR 1.298, P = 0.0040 and aOR 1.007, P = 0.0195, respectively)." (PMID 29777150, 2018). "Previous studies have shown low serum albumin or high serum CRP concentrations to be risk factors for bacteremia in patients with CAP; our findings are consistent with this." (PMID 29382316, 2018). "NLR is thought to be an early marker of bacteremia given its positive association with CRP, and NLR has also been associated with placental inflammation when NLR ≥ 6.48 and CRP ≥ 71 nmol/L." (PMID 28571565, 2017). "The results of univariate analysis displayed statistical significance in seven risk factors for neonatal bacterial sepsis including the age in days, birth weight, parity, gestational age, CRP, sCD14-ST, and TBIL value (P < 0.05)." (PMID 28758124, 2017). "Few studies compared the diagnostic value of procalcitonin with a combination of other tests including lactate and high-sensitivity C-reactive protein in the prediction of pathogenic bacteremia in emergency department adult patients." (PMID 29201568, 2017). "Among these biomarkers, procalcitonin (PCT) and high-sensitivity C-reactive protein (hs-CRP) are the main diagnostic markers used for bacterial sepsis." (PMID 27389015, 2016). "S. aureus meningitis (IE: 59%), persistent bacteremia at 48 hours (IE: 25%) and C-reactive protein > 190 mg/L (IE: 15%) were also independently associated with IE." (PMID 26020939, 2015). "CRP concentrations were significantly higher if CAP was associated with bacteremia (23.3 (14.9–35.1) versus 16.1 (8.8–24.1) mg/dL)." (PMID 24286072, 2013). "In univariate linear mixed model analysis, 10/citrulline, the type of conditioning regimen, neutropenia and bacteremia were significantly associated with log CRP." (PMID 21188146, 2010). "On the other hand, there is no data about the value of diagnostic tests (white blood cell count, C-reactive protein, procalcitonin, etc.)to predict bacteremia or meningitis in newborns and small infants with cellulitis." (PMID 20062760, 2009). "They therefore included the variable of CRP < 100 mg/L in a classification algorithm for low risk of bacteremia." (PMID 18957115, 2008). "In CoNS bacteremia, especially in very preterm infants, attenuated inflammatory responses may lower CRP levels; however, this may increase the risk of false negatives." (PMID 40723124, 2025).
bacteremia (continued). "Finally, bacterial relapse within CAZ-AVI patients was associated with only significantly lower WBCs and CRP blood counts than those of the bacteremia-receded patients." (PMID 38534700, 2024). "Failure to reduce CRP concentration to less than 50% after 72-96 hours has been associated with inappropriate antibiotic therapy and possible parapneumonic complications, such as empyema or bacteremia." (PMID 39575025, 2024). "Furthermore, the logistic regression analysis revealed that higher body temperature at triage, elevated pulse rates at triage, increased neutrophil counts, and higher CRP levels were all associated with an increased likelihood of bacteremia." (PMID 37679686, 2023). "Future investigations might benefit from a comprehensive evaluation of ESR and CRP, potentially revealing additional insights into their diagnostic relevance in bacteremia." (PMID 37891995, 2023). "In present study we found that community acquisition of bacteremia and elevated CRP were independently associated with the detection of infectious foci in SAB, while primary bacteremia and increased pre-scan blood glucose level were significantly associated with lack of findings on FDG PET/CT." (PMID 37640802, 2023). "Moreover, higher levels of both neutrophils and CRP were also associated with an increased risk of bacteremia in newborns." (PMID 37679686, 2023). "Higher BT at triage, increased neutrophil counts, and elevated CRP levels could be helpful clinical factors for predicting the risk of bacteremia in young febrile infants with pyrexia admitted to the PED." (PMID 37679686, 2023). "Furthermore, hepcidin appears to be a more sensitive and treatment-responsive acute-phase marker than ferritin in patients with bacteremia and parallels or even exceeds the diagnostic accuracy of CRP." (PMID 35741214, 2022). "Significant differences with respect to hepatic dysfunction, shock, the event with seawater or seafood contact, bacteremia, C-reactive protein, mean platelet counts, and the Laboratory Risk Indicator for Necrotizing Fasciitis (LRINEC) score were observes between V. vulnificus and MRSA groups." (PMID 34372768, 2021). "The radiographic evidence of effusion or necrotizing pneumonia was associated with bacteremia (P<0.11) while the binary logistics regression analysis showed that significantly elevated CRP (> 300 mg/L) was associated with a true-positive blood culture (p<0.01)." (PMID 32582483, 2020). "In a Japanese cohort with MSSA bacteraemia (excluding people who died), community-acquired bacteremia, unknown source of bacteremia, persistent fever (>72 hours), delayed treatment, and CRP concentration were positively associated with metastatic complications." (PMID 38767234, 2024). "Several studies attest to the fact that it causes a significant rise in CRP values, and often with levels comparable to those seen in bacteremia; in Tanzania it outperformed WBC and ANC at predicting bacterial infection, but could not distinguish between bacterial infection and malaria on its own." (PMID 37478118, 2023). "In addition, transient bacteremia and inappropriate timing might be the other causes of these inconsistencies between high levels of CRP and PCT with peripheral blood cultures." (PMID 33178372, 2020). "Therefore, a substantial rise of CRP could indicate diagnostic situations, where the inflammatory stimulus – e.g. transient bacteremia – may already have disappeared by the time the BC is drawn." (PMID 18957115, 2008). "Considering that CRP has been shown to predict persistent MRSA bacteremia, these findings further support that a 109 CFU IV dose of MRSA USA 300 is capable of establishing sublethal systemic infections in cynomolgus macaques." (PMID 40766078, 2025). "Hemoglobin, cholesterol, and albumin levels were significantly lower in the bacteremia group, while platelet count, CRP, PCT, glucose, and triglycerides were significantly elevated (all p < 0.05)." (PMID 40792110, 2025).